MTA1 (metastasis associated 1)
Diseases named in the same sentence as MTA1 in open-access papers (continued):
Sharing a sentence is not in itself a finding about the gene and the disease.
pancreatic cancer (7 papers, 2004 to 2024). "After browsing the abstracts and full text, 5 studies on MTA1 and EC, 3 studies on MTA and GC, 2 studies on MTA1 and CRC, 2 studies on MTA1 and liver cancer and one study on MTA1 and pancreatic cancer met the inclusion criteria, respectively." (PMID 28570554, 2017). "The results demonstrate that enhanced expression of MTA1 triggers the development of motile, invasive pancreatic carcinoma cells by altering the organisation of the cellular cytoskeleton." (PMID 14735193, 2004). "Since PANC-1 cells express only low levels of endogenous MTA1 mRNA, we chose this cell line to investigate the effects of heterologous MTA1 expression on the cell biological properties of pancreatic carcinoma cells." (PMID 14735193, 2004). "Enhanced expression of MTA1 might be of considerable importance for the progression to malignancy of pancreatic neoplasms." (PMID 14735193, 2004). "In the present study, we have examined whether enhanced expression of MTA1 in itself modifies the malignant phenotype of pancreatic carcinoma cells." (PMID 14735193, 2004). "Furthermore, MTA1-expressing PANC-1 pancreatic carcinoma cells exhibited distinct changes in arrangement and localisation of cytoskeletal proteins, such as keratins and IQGAP1." (PMID 14735193, 2004). "To address the functional consequences of MTA1 expression in pancreatic carcinoma cells, we have established PANC-1 pancreatic carcinoma cells that stably express MTA1 as an enhanced green fluorescent fusion protein (EGFP–MTA1)." (PMID 14735193, 2004). "In pancreatic cancer tissues, the MTA1 mRNA expression levels seem to be correlated with lymph node metastasis, whereas in established pancreatic carcinoma cell lines MTA1 mRNA levels were not correlated with the cells' propensity to metastasise." (PMID 14735193, 2004). "How MTA1 promotes the more motile, invasive phenotype of PANC-1 pancreatic carcinoma cells is currently unknown." (PMID 14735193, 2004). "Thus no definitive role of MTA1 in the progression of pancreatic cancer has yet been established." (PMID 14735193, 2004).
breast tumor (6 papers, 2012 to 2022). "As the TCGA data shows, the mRNA level of the MTA family, containing MTA1, MTA2 and MTA3, is higher in breast tumor tissues than in normal tissues (p=1e-12 in MTA1, p=9.7e-9 in MTA2, p<2.22e-16 in MTA3)." (PMID 33282725, 2020). "Breast tumors from HFD group exhibited elevated expression of MTA1, β-catenin and cyclin D1 which was efficiently abrogated by HNK treatment." (PMID 26036628, 2015). "For example, deregulation of the ERα co-regulators SRC3 (AIB1), SRC2 and MTA1 was reported in breast tumors." (PMID 22812534, 2012). "MTA1s, another MTA1 spliced variant, but not full-length MTA1, has been reported to sequester the estrogen receptor in the cytoplasm and contribute to poor prognosis of breast tumors." (PMID 27323415, 2016).
endometrial cancer (6 papers, 2014 to 2024). Primary or metastatic malignant neoplasm involving the endometrium (mucous membrane that lines the endometrial cavity). "In 2014, Kong provided the direct evidence of miR-30c specific binding to the 3' UTP of MTA-1(Metastasis Associated 1), which further demonstrated that miR-30c was negatively related with endometrial cancer progression through MTA-1 inhibition." (PMID 32201529, 2020). "Reassuringly, the same association between MTA1 and AKT/mTOR/4EBP1 was recently reported in endometrial cancer, in which miR-30c/MTA1 axes regulated cell proliferation, migration, and invasion via AKT/mTOR signaling defining MTA1 as a therapeutic target in endometrial cancer." (PMID 38611022, 2024). "Moreover, in endometrial cancer, miR-30c executes its tumor-suppressive role by targeting MTA1, thereby curtailing cancer cell proliferation, migration, and invasion." (PMID 39551792, 2024). "In 2012, Zhou found that miRNA-30c repressed the metabolism related gene-metabolism associated gene 1 (MTA1) in Ishikawa (estrogen receptor positive) and HEC-1-B (estrogen receptor negative) endometrial cancer cell lines, and played an inhibitory role in endometrial cancer progression." (PMID 32201529, 2020).
esophageal cancer (6 papers, 2008 to 2025). A primary or metastatic malignant neoplasm involving the esophagus. "The expression of MTA1 and its encoded protein, MTA1, have been found to correlate with the malignant properties of numerous human cancers, including cancer of the esophagus, breast, pancreas, colon, stomach, liver and prostate." (PMID 25009653, 2014). "By improving the understanding of the expression of HDAC1 and MTA1 in esophageal carcinogenesis, targeted esophageal cancer chemotherapy may be developed." (PMID 25009653, 2014). "Esophageal cancers have been investigated for MTA1/MTA1 overexpression and those esophageal cancer cells that were overexpressing MTA1/MTA1 have shown significantly higher frequencies of adventitial invasion and lymph node metastasis, as well as higher rates of lymphatic involvement." (PMID 25009653, 2014). "In subgroup analyses based on study quality and tumor type, MTA1 overexpression was obviously related to clinical parameters, such as lymph node metastasis and TNM stage, and was also associated with prognosis of patients with gastrointestinal or esophageal cancer." (PMID 28570554, 2017). "Human head and neck tumours and oesophageal cancer tissues expressed higher levels of MTA1 transcripts than matched non-tumour tissues (data not shown)." (PMID 18949081, 2008).
prostate tumor (6 papers, 2013 to 2024). "The metastasis-associated protein 1/protein kinase B (MTA1/AKT) signaling pathway has been shown to cooperate in promoting prostate tumor growth." (PMID 38611022, 2024). "Taken together, these results demonstrate that pterostilbene treatment inhibits tumor cell proliferation and angiogenesis and induces apoptosis in Pten-loss prostate tumors, at least in part, due to inhibition of MTA1." (PMID 26943043, 2016). "Here, we report on a previously unknown mechanism-based importance of the chromatin modifier MTA1 in Pten loss-driven prostate tumors." (PMID 26943043, 2016). "We previously found that MTA1 expression was decreased in Il-17rc-null mouse prostate tumors compared to Il-17rc-expressing mouse prostate tumors." (PMID 31281798, 2019). "In this study, we have demonstrated that MTA1 promotes prostate tumor growth and formation of bone metastasis, at least in part, by positively regulating CTSB expression in the primary tumor cells." (PMID 30027683, 2018). "Of note, the fact that our intracardiac shMTA1 xenografts exhibited reduced formation of bone metastasis suggests that it is possible to prevent homing of primary prostate tumor cells to the bone microenvironment by targeting MTA1." (PMID 30027683, 2018). "In this study, we systematically analyzed the in vitro and in vivo role of MTA1 in prostate tumor cell metastatic potential, tumor growth, and formation of metastasis using subcutaneous (s.c.)and experimental bone metastasis xenograft mouse models." (PMID 30027683, 2018). "Collectively, this data demonstrate a more potent MTA1/HIF‐1α‐targeted response to Pter/SAHA combination treatment than to single therapies both in murine prostate tumors and in PCa cell lines." (PMID 29024573, 2017). "Altogether, our results indicate MTA1 as a major contributor in prostate tumor malignant progression, and support the use of strategies targeting MTA1." (PMID 23469203, 2013). "We showed that MTA1 ablation profoundly suppressed the growth of prostate tumors and the ability of tumor cells to colonize the bone by inhibiting their migratory and invasive properties through repression of cathepsin B (CTSB), a cysteine protease that plays a critical role in bone metastasis." (PMID 30027683, 2018). "In this study, we hypothesized that treatment of prostate tumors with a combination of Pter and SAHA could be a more effective and less toxic way to target MTA1‐associated angiogenesis." (PMID 29024573, 2017). "In this study, we examined whether inhibition of MTA1/HDAC using combination of Pter and a clinically approved HDAC inhibitor, SAHA (suberoylanilide hydroxamic acid, vorinostat), which also downregulates MTA1, could block prostate tumor progression in vivo." (PMID 29024573, 2017). "Based on our previous studies suggesting a possible inverse relationship between MTA1 and PTEN, we hypothesized that MTA1-targeted therapy would be effective for blocking Pten loss-driven prostate tumor growth and progression." (PMID 26943043, 2016). "To compare the in vivo efficacy of resveratrol and PTER, and to study the role of MTA1 in prostate tumor growth and progression, we utilized clinically relevant orthotopic mouse model, in which human PCa cells expressing or silenced for MTA1 can grow in an environment related to their tissue origin." (PMID 23469203, 2013). "Marked increase in MTA1 levels, which is an indicator of advanced castrate‐resistant prostate tumors, might be an important factor in endorsing CTSB‐mediated degradation of basement membrane and in the ability of primary prostate tumor cells to undergo E‐cad‐mediated EMT." (PMID 30027683, 2018). "The expression of both MTA1 and HIF‐1α at protein and mRNA levels in prostate tumor tissues from mice treated with agents was significantly reduced compared to vehicle controls." (PMID 29024573, 2017).
prostate tumor (continued). "We found that in MTA1‐high group, 69.2% showed high levels of HIF‐1α, whereas in MTA1‐low group, 83.3% showed low HIF‐1α, once again indicating positive relationship between MTA1 and HIF‐1α expression in prostate tumors." (PMID 29024573, 2017). "However, the exact role of MTA1 and its downstream signaling mechanisms that mediate MTA1‐activated prostate tumor cell invasion and colonization into the bone are not well understood." (PMID 30027683, 2018).
liver cancer (5 papers, 2013 to 2023). An epithelial or non-epithelial malignant neoplasm that arises from the liver. "In summary, our study demonstrates that SMYD3 specifically associates with the NuRD (MTA1/2) complex to form a complex in liver cancer cells, providing new insights into how SMYD3 regulates transcription by coordinating with distinct partner protein complexes." (PMID 36575438, 2022). "The metastasis-associated protein 1 (MTA1) gene is one of the important transcriptional target of HBx protein; It has been found that MTA1 activates hypoxia-inducible factor 1α and vascular endothelial growth factor which contributes to angiogenesis in hepatic cancer." (PMID 23991421, 2013). "Further studies demonstrated that the effect of miR-30e in liver cancer may be through targeting MTA1 for epithelial to mesenchymal transition and P4HA1 for proliferation suppression." (PMID 28969071, 2017).
metastatic disease (5 papers, 2004 to 2024). "MTA1 is a founding member of this family and was first identified as a metastasis-associated tumor gene differentially expressed in rat metastatic tumors." (PMID 28570554, 2017). "While metastasis‐associated protein 1 (MTA1) is highly overexpressed in metastatic tumors and bone metastatic lesions, its exact role in the development of metastasis is unknown." (PMID 30027683, 2018). "Comparative analyses revealed that MTA1 mRNA was differentially expressed in nonmetastatic and metastatic tumours, thus pointing towards a role of MTA1 in enhancing the metastatic potential of malignant tumour cells." (PMID 14735193, 2004). "In conclusion, the presented work identified the seven genes EMILIN3, MTA1, SV2B, TMPRSS6, ACVR1C, NFAT5 and SMC3 associated with the formation of colorectal BM during the course of disease but not with liver metastasis or non-metastatic disease." (PMID 38558282, 2024).
mammary adenocarcinoma (3 papers, 2004 to 2023). "MTA1/MTA1, a constituent of the nucleosome-remodelling and –deacetylation (NuRD) complex, was originally isolated by differential cDNA hybridization from rat mammary adenocarcinoma." (PMID 21082030, 2010). "A correlated gene of note is the MTA1 gene, which has been associated with mammary adenocarcinoma cells; although the role has not been fully investigated, the presence of this protein/gene may be useful in improving cattle health." (PMID 37761929, 2023).
squamous cell carcinoma (3 papers, 2015 to 2025). A carcinoma arising from squamous epithelial cells. "Further analysis found that the frequency of MTA1 overexpression was lower in squamous cell carcinoma (SCC) and small cell lung cancer (SCLC) than in adenocarcinoma (ADC)." (PMID 26698569, 2015). "Moreover, an additional study assessed the OS of patients with squamous cell carcinoma (SCC) and found that patients with elevated MTA1 levels had a worse prognosis." (PMID 40660330, 2025). "In non-keratinizing squamous cell carcinoma and in vulvar carcinoma of the condylomatous type, the expression of MTA1 in the cytoplasm was significantly increased compared to the other two tumor subtypes (p = 0.038)." (PMID 36689059, 2023). "Non-keratinizing squamous cell carcinoma and vulvar carcinoma of the condylomatous type showed an increased expression of MTA1 in the cytoplasm compared to keratinizing squamous cell carcinoma and vulvar carcinoma of the verrucous type." (PMID 36689059, 2023). "Cytoplasmatic expression of MTA1 was significantly increased in non-keratinizing squamous cell carcinoma and in vulvar carcinoma of the condylomatous type, compared to keratinizing squamous cell carcinoma and vulvar carcinoma of the verrucous type." (PMID 36689059, 2023).
triple-negative breast carcinoma (3 papers, 2019 to 2025). An invasive breast carcinoma which is negative for expression of estrogen receptor (ER), progesterone receptor (PR), and human epidermal growth factor receptor 2 (HER2). "In triple-negative breast cancer (TNBC), upregulated circ-UBAP2 binds to and inhibits miR-661, which promotes high expression of the MTA1 oncogene that activates TNBC cell proliferation and migration." (PMID 31584877, 2019). "To testify our hypothesis, we overexpressed MTA1 in MDA-MB-231 cells, a triple negative breast cancer cell line." (PMID 30642362, 2019).
carcinoma of the stomach (2 papers, 2012 to 2018). "In fact, MTA1 gene expression correlates with tumor invasion, metastasis and that a high expression of MTA1 mRNA may be a potential indicator for assessing the malignant potential of colorectal and gastric carcinomas." (PMID 29467924, 2018).
glioma (2 papers, 2008 to 2013). A benign or malignant brain and spinal cord tumor that arises from glial cells (astrocytes, oligodendrocytes, ependymal cells). "In yet another study, the protein levels of the SOX2-associated protein Mta1 are elevated in a glioma tumor model." (PMID 23667531, 2013). "However, the significance of MTA1 in the malignancy progression of gliomas has rarely been considered." (PMID 18940013, 2008). "In the current study, the particular amplification of MTA1 in GSCs derived from the recurrent tumor makes it reasonable to conjecture that MTA1 activation may contribute to both the aggression of GSCs and the malignancy progression of gliomas." (PMID 18940013, 2008).
head and neck cancer (2 papers, 2020 to 2025). A primary or metastatic malignant neoplasm affecting the head and neck. "Studies have revealed that MTA1 played an oncogenetic role in cancers, including head and neck cancer." (PMID 32678829, 2020).
male infertility (2 papers, 2011 to 2022). The inability of the male to effect fertilization of an ovum after a specified period of unprotected intercourse. "The fact that decrease of MTA1 could be detected even earlier than the beginning of the damage of testicular cells after heat stress also warrants its diagnostic potential for male infertility induced by hyperthermia." (PMID 22022494, 2011). "Among the other validated hits were proteins involved in the ubiquitin proteasome system (STAMBP and MYLIP), transcription (MTA1, PKNOX2), translation (EIF4E3), male infertility (RABL2A, DAZAP1), and virus-induced oncogenesis (MTA1)." (PMID 35452674, 2022).
malignant salivary gland neoplasm (2 papers, 2016 to 2025). "According to these findings, MTA1 dysregulation in a subset of salivary gland cancer may compromise ERβ's tumor suppressor function, leading to aggressive phenotypes." (PMID 40660330, 2025). "Our findings demonstrate that MTA1 was significantly overexpressed in malignant salivary gland neoplasm in comparison to a lower level in benign pleomorphic adenoma, suggesting that MTA1 protein might be involved in carcinogenesis." (PMID 26878004, 2016). "As a result, the MTA1-ERβ axis may be a novel therapeutic target for salivary gland cancer." (PMID 40660330, 2025).
metastatic prostate carcinoma (2 papers, 2012 to 2017). A carcinoma that arises from the prostate gland and has spread to other anatomic sites. "The metastasis‐associated protein 1(MTA1)/histone deacetylase (HDAC) unit is a cancer progression‐related epigenetic regulator, which is overexpressed in hormone‐refractory and metastatic prostate cancer (PCa)." (PMID 29024573, 2017).
mucoepidermoid carcinoma (2 papers, 2016 to 2025). A carcinoma morphologically characterized the presence of cuboidal mucous cells, goblet-like mucous cells, squamoid cells, cystic changes, and a fibrotic stromal formation. "Fifty-six samples of salivary gland tumors from the Khalili Hospital archive, including 20 cases of pleomorphic adenoma, 17 cases of mucoepidermoid carcinoma, 19 cases of ACC, and 23 cases of normal salivary gland tissues were chosen for immunohistochemical analysis of MTA1." (PMID 26878004, 2016).
oral cancer (2 papers, 2019 to 2020). "In accordance with slope value for cell proliferation assay, overexpressed MTA1 promoted the growth rate of oral cancer SAS cells." (PMID 32678829, 2020). "IHC analysis showed that JMJD5 and MTA1 are expressed in oral cancer SC179-PDTX, and these expressions were significantly downregulated after silibinin administration in clinical tumor-bearing mice compared with controls." (PMID 32678829, 2020). "However, the signaling pathway through which silibinin represses JMJD5 and MTA1 in oral cancer cells remains unknown." (PMID 32678829, 2020). "Furthermore, according to IHC assay, JMJD5 was correlated with MTA1 in patients with oral cancer." (PMID 32678829, 2020). "Therefore, this study used a preclinical PDTX model and oral cancer cell line to investigate whether the anticancer effects of silibinin on cell proliferation in oral cancer are exerted through downregulation of MTA1/JMJD5." (PMID 32678829, 2020). "Moreover, silibinin could downregulate JMJD5 and MTA1 in oral cancer." (PMID 32678829, 2020). "In addition, silibinin suppressed oral cancer cell proliferation through downregulation of JMJD5 and MTA1 in vitro, in vivo, and in PDTX." (PMID 32678829, 2020).
osteosarcoma (2 papers, 2008 to 2019). A usually aggressive malignant bone-forming mesenchymal neoplasm, predominantly affecting adolescents and young adults. "Over-expression of MTA-1 has been noted in high-grade osteosarcoma tumor samples with little to no expression in low-grade samples." (PMID 32039013, 2019). "In a series of 53 osteosarcoma specimens, MTA-1 was expressed in 81% of high-grade tumor samples, but in none of the low grade tumors." (PMID 32039013, 2019).
prostate adenocarcinoma (2 papers, 2015 to 2018). "As such, the identification of YB-1 and MTA1 as predictive biomarkers represents a potentially important advancement, which may allow clinicians to prognosticate the aggressive or indolent nature of a prostate adenocarcinoma that arises within a patient." (PMID 25797255, 2015).